SAC3D1 (SAC3 domain containing 1)
Description:
Involved in centrosome duplication and mitotic progression.
Synonyms: SHD1; HSU79266
Gene: Protein-coding gene on chromosome 11 (65,040,901 to 65,044,828, forward strand). Ensembl gene ENSG00000168061.
Subcellular location: Cytoplasm, cytoskeleton, microtubule organizing center, centrosome; Cytoplasm, cytoskeleton, spindle
Subcellular location (Human Protein Atlas): Cytosol
Genetic constraint (gnomAD): Loss-of-function variants: 10 observed, 6.18 expected, observed/expected ratio (o/e) 1.62, 90% interval 0.94 to 1.95. That is too few expected variants to judge how well the gene tolerates losing a copy. Missense variants: 482 observed, 402.61 expected, observed/expected ratio (o/e) 1.2, 90% interval 1.11 to 1.29. Synonymous variants: 241 observed, 181.95 expected, observed/expected ratio (o/e) 1.32, 90% interval 1.19 to 1.47.
Homologues: Orthologues: chimpanzee SAC3D1 (99% identical), macaque SAC3D1 (97% identical), dog SAC3D1 (85% identical), pig SAC3D1 (84% identical), guinea pig SAC3D1 (82% identical), mouse Sac3d1 (77% identical), rat Sac3d1 (76% identical), tropical clawed frog sac3d1 (37% identical), zebrafish sac3d1 (36% identical), Drosophila melanogaster CG3437 (27% identical), Caenorhabditis elegans tag-115 (22% identical). Paralogues in human: MCM3AP (30% identical), LENG8 (18% identical).
Diseases named in the same sentence as SAC3D1 in open-access papers:
SAC3D1 is named in the same sentence as 9 diseases in open-access papers, as found by Europe PMC text mining. Sharing a sentence is not in itself a finding about the gene and the disease. The quoted sentences say what the papers report.
hepatocellular carcinoma (3 papers, 2018 to 2024). A malignant tumor that arises from hepatocytes. "A number of studies reported that SEMA3F, UCK2, NOL10, RAP2A, ZIC2 and SAC3D1 are associated with prognosis and tumour immune infiltration in hepatocellular carcinomas." (PMID 34760691, 2021). "Additionally, our findings suggest SAC3D1 as a promising therapeutic target for hepatocellular carcinoma, potentially revealing new mechanisms underlying liver cancer development." (PMID 39100078, 2024). "Considering all these results, we conclude that the abnormally high expression of SAC3D1 is highly associated with the prognosis and drug treatment of patients with hepatocellular carcinoma (HCC)." (PMID 39100078, 2024). "To investigate how SAC3D1 affects the progression of hepatocellular carcinoma (HCC), we conducted enrichment analysis of BIOCARTA, Hallmark, REACTOME, PID, and KEGG pathways in samples with high SAC3D1 expression using the GSEA database." (PMID 39100078, 2024). "To further validate the impact of SAC3D1 on hepatocellular carcinoma (HCC), we conducted in vitro experiments using two HCC cell lines, Huh7 and HCCLM3, expressing high levels of SAC3D1." (PMID 39100078, 2024). "SAC3D1, however, is associated with centrosome abnormality, although its prognostic potential has not been evaluated in hepatocellular carcinoma (HCC)." (PMID 30353105, 2018). "Cellular immunofluorescence staining and Western blot assays of hepatocellular carcinoma cells in the SAC3D1 knockdown expression group exhibited reduced expression levels of Aurora B and TTK, implying that SAC3D1 knockdown mitigated SAC function dysregulation." (PMID 39100078, 2024).
breast carcinoma (1 paper, 2024). "ATG2A exhibits mutations in breast cancer, FRMD8 plays a tumor-suppressive role in breast cancer progression, ARSG is negatively correlated with positive prognosis, and differentially expressed genes upregulated by SAC3D1 are involved in regulating the cell cycle pathways in breast cancer cells." (PMID 39720180, 2024).
breast ductal carcinoma (1 paper, 2021). "In the Richardson dataset, the CCDC167 gene and its co-expressed genes, such as SAC3D1, SPC24, CENPM and DEPDC1B, were substantially upregulated in breast ductal carcinoma compared to the normal group." (PMID 33461170, 2021).
hepatitis C (1 paper, 2018). "In the GSE10186 subgroup data analysis, SAC3D1 showed high C-index values in patients with hepatitis C (0.673)." (PMID 30353105, 2018).
liver cancer (1 paper, 2024). An epithelial or non-epithelial malignant neoplasm that arises from the liver. "High expression of SAC3D1 in liver cancer patients was associated with poor overall survival (OS) and recurrence-free survival (RFS)." (PMID 39100078, 2024). "The findings indicated prevalent SAC3D1 expression in human liver cancer tissues, with SAC3D1 expression augmenting the proliferation and invasion of liver cancer cells, suggesting its promotional role in HCC progression." (PMID 39100078, 2024). "Additionally, through immunofluorescence staining, we found that compared to the control group, liver cancer cells with knocked-down SAC3D1 exhibited less spindle dysfunction: there was an increase in multipolar and monopolar spindle occurrences." (PMID 39100078, 2024).
renal carcinoma (1 paper, 2018). A carcinoma arising from the epithelium of the renal parenchyma or the renal pelvis. "These roles of SAC3D1 during the cell cycle support its prognostic significance in hepatic and renal cancers." (PMID 30353105, 2018).
cancer (5 papers, 2018 to 2024). A tumor composed of atypical neoplastic, often pleomorphic cells that invade other tissues. "SAC3D1 is involved in immune response, as well as its association with metabolism-related signaling pathways, positions it as a key player in T cell exhaustion and provides valuable insights for prognosis and immunotherapy effectiveness in various cancers." (PMID 38629071, 2024). "For instance, genes such as SAC3D1, NELFCD, and TAF9 (TATA-box binding protein associated factor 9) were implicated in the DNA repair pathway and are associated with survival in some cancers." (PMID 33477315, 2021). "SAC3D1 expression levels were observed to be significantly higher in cancer tissues than in their matched normal tissues." (PMID 30353105, 2018). "To evaluate the expression status of SAC3D1 in HCC, we compared its expression levels in cancer and matched normal liver tissues using ICGC data." (PMID 30353105, 2018).
tumor (4 papers, 2021 to 2024). "We discovered through immunofluorescence staining that the expression of TTK was reduced in tumor cells with knocked-down SAC3D1." (PMID 39100078, 2024). "Subsequently, immunofluorescence staining of the harvested tumor tissues revealed a markedly weaker expression of SAC3D1 in the knocked-down group compared to the control group." (PMID 39100078, 2024). "This discovery delineates the downstream signaling pathway of SAC3D1 in inducing tumor progression in HCC." (PMID 39100078, 2024). "The results showed that, compared to adjacent non-tumor tissues, the expression of RAD23A, SAC3D1, and PSIP1 was significantly upregulated in OS tissues." (PMID 38629071, 2024). "Similarly, after immunohistochemical staining of patient tumor tissues and adjacent non-cancerous tissues, we found that SAC3D1 was significantly overexpressed in the tumor tissues." (PMID 39100078, 2024).
SAC3D1 also shares sentences with these, for which no sentence is quoted: gastric cancer (1 paper).